ZMYND15 (zinc finger MYND-type containing 15)
Description:
Acts as a transcriptional repressor through interaction with histone deacetylases (HDACs). May be important for spermiogenesis.
Synonyms: DKFZp434N127; SPGF14
Tractability: No criterion of Open Targets' tractability assessment is met for any kind of drug.
Gene: Protein-coding gene on chromosome 17 (4,739,108 to 4,746,119, forward strand). Ensembl gene ENSG00000141497.
Subcellular location: Nucleus; Cytoplasm
Subcellular location (Human Protein Atlas): Nuclear speckles; Cytosol
Gene Ontology:
Molecular function: histone deacetylase binding
Biological process: negative regulation of DNA-templated transcription; spermatid development
Cellular component: cytoplasm; nucleus
Genetic constraint (gnomAD): Loss-of-function variants: 56 observed, 82.55 expected, observed/expected ratio (o/e) 0.68, 90% interval 0.55 to 0.85. The upper end of that interval is the gene's LOEUF score, 0.85, which puts it in group 3 of 6, group 1 being the genes least tolerant of losing a copy. Missense variants: 925 observed, 977.25 expected, observed/expected ratio (o/e) 0.95, 90% interval 0.9 to 1. Synonymous variants: 399 observed, 388.77 expected, observed/expected ratio (o/e) 1.03, 90% interval 0.94 to 1.12.
Homologues: Orthologues: chimpanzee ZMYND15 (99% identical), macaque ZMYND15 (94% identical), dog ZMYND15 (88% identical), pig ZMYND15 (86% identical), rabbit ZMYND15 (86% identical), rat Zmynd15 (84% identical), guinea pig ZMYND15 (84% identical), mouse Zmynd15 (84% identical), tropical clawed frog zmynd15 (33% identical), Drosophila melanogaster CG18213 (12% identical), Drosophila melanogaster Smyd4-2 (9% identical), Drosophila melanogaster Smyd4-1 (8% identical), and 6 more. Paralogues in human: SMYD4 (12% identical), SMYD2 (11% identical), SMYD1 (9% identical), SMYD3 (8% identical), SMYD5 (8% identical).
Diseases named in the same sentence as ZMYND15 in open-access papers:
ZMYND15 is named in the same sentence as 4 diseases in open-access papers, as found by Europe PMC text mining. Sharing a sentence is not in itself a finding about the gene and the disease. The quoted sentences say what the papers report.
Azoospermia (5 papers, 2016 to 2024). Absence of any measurable level of sperm,whereby spermatozoa cannot be observed even after centrifugation of the semen pellet. "Moreover, mutations in the zinc finger MYND-type-containing 15 gene (ZMYND15) have been associated with non-obstructive azoospermia (NOA) and severe oligozoospermia." (PMID 38732193, 2024). "By analyzing the relationship between these genes and phenotype, we speculated that case 1 showed azoospermia, which may have been related to the disruption of the MSH5 or/and ZMYND15 gene." (PMID 36626513, 2022). "It has been demonstrated that the lack of ZMYND15 produces nonobstructive azoospermia and severe oligozoospermia; additionally, another research suggests that it may potentially be linked to teratozoospermia." (PMID 36292606, 2022).
male infertility (2 papers, 2016 to 2018). The inability of the male to effect fertilization of an ovum after a specified period of unprotected intercourse. "Remarkably, the transcripts encoding genes such as ZMYND15, KLHL10, TDRD1, TSSK2 and DNAJB13, which are linked to male infertility in other species, were differentially expressed among the treatments." (PMID 30697164, 2018).
tumor (1 paper, 2023). "After that, five tumor antigens (ALOX15B, HS3ST2, PIGR, ZMYND15, and LIMK1) were identified to be candidates for the mRNA-based vaccine development, all of which were correlated with survival time of PRCC patients and the degree of APC infiltration." (PMID 36836593, 2023). "Five tumor antigens, including ALOX15B, HS3ST2, PIGR, ZMYND15 and LIMK1, were identified for PRCC, which were correlated with patients’ prognoses and infiltration levels of APCs." (PMID 36836593, 2023). "Taken together, five tumor antigens (ALOX15B, HS3ST2, PIGR, ZMYND15, and LIMK1), with potentially provocative effects on immunological functions, were identified and considered as eligible candidates for anti-PRCC mRNA vaccine development." (PMID 36836593, 2023).
ZMYND15 also shares sentences with these, for which no sentence is quoted: teratozoospermia (2 papers).